CCND2 (cyclin D2)
Diseases named in the same sentence as CCND2 in open-access papers (continued):
Sharing a sentence is not in itself a finding about the gene and the disease.
colorectal cancer (26 papers, 2014 to 2025). A primary or metastatic malignant neoplasm that affects the colon or rectum. "Recently, a genome-wide association study (GWAS) showed the CCND2 inherited genetic variations are associated with the risk of colorectal cancer in Europeans and Asians." (PMID 24743557, 2014). "CCND2 is a cell cycle protein that has been associated with progression in colorectal cancer." (PMID 38731867, 2024). "Moreover, correlation analysis revealed that SNHG1 expression was positively associated with CCND2 expression in 30 colorectal cancer tissues (P = 0.036)." (PMID 30266084, 2018). "According to previous studies, the CCND2 gene is a potential target of miR-1297, which inhibits the progression of colorectal cancer by inhibiting the transcription of CCND2 in colorectal cancer cells." (PMID 36968605, 2023). "Perhaps more importantly, previous study found that UCHL1 promotes progression of colorectal cancer cell lines via the activation of CCND2, which is a downstream target of the Wnt β-catenin/TCF pathway." (PMID 34257568, 2021). "Collectively, these results suggest that SNHG1 released CCND2 by sequestering endogenous miR-154-5p in colorectal cancers cells." (PMID 30266084, 2018). "Expression of CCND2 has been shown to be correlated with persistence of colorectal cancer." (PMID 38731867, 2024). "Furthermore, another study found that during RT, the JAK2/STAT3 signaling pathway was activated, which in turn activated downstream CCND2 expression and enhanced CSCs properties, leading to radioresistance in colorectal cancer." (PMID 38355684, 2024). "For instance, an increase in CCND2 has been reported to promote cell growth in colorectal cancer." (PMID 37204480, 2023). "The expression of CCND2 RNA and protein was increased in colorectal cancer (CRC)." (PMID 33005182, 2020). "Importantly, CCND2 silencing impaired SNHG1 overexpression mediated increases in colorectal cancer cells growth and proliferation." (PMID 30266084, 2018). "Moreover, miR-154-5p was observed to be down-regulated in colorectal cancer tissues, CCND2 was observed to be up-regulated in colorectal cancer tissues." (PMID 30266084, 2018). "(i) CCND2 expression analyzed in colorectal cancer samples and normal samples from TCGA cohort." (PMID 30266084, 2018). "Mechanistic investigations revealed that SNHG1 could exhibit different regulatory mechanisms in the nucleus and cytoplasm, and it could promote the development of colorectal cancer by regulating CCND2, KLF2 and CDKN2B expression." (PMID 30266084, 2018). "(j) The relation between CCND2 and SNHG1 expression analyzed in colorectal cancer samples from TCGA cohort (n = 478, r = 0.21, P = 0.003)." (PMID 30266084, 2018). "The results revealed that Cyclin D1, Cyclin D2, CDK4 and CDK6 were all decreased in si-SNHG1-transfected colorectal cancer cells." (PMID 30266084, 2018). "Subsequently, they found CCND2 was directly activated by JAK2/STAT3 axis, which served as a critical aspect to promote the resistance of colorectal cancer to radiotherapy and knock down of CCND2 significantly abolished the self‐renewal activity of colorectal CSC group." (PMID 41346572, 2025). "CCND2 and CCND3 were used as positive markers for cell cycle in colorectal cancer." (PMID 34548081, 2021). "Indeed, in colorectal cancer, the activation of STAT3 following irradiation allowed the cells to be intrinsically radioresistant through the activation of Cyclin D2 (CCND2) transcription." (PMID 34141616, 2021).
colon carcinoma (17 papers, 2010 to 2025). "LINC01567 can regulate the proliferation of colon cancer stem cells (CSCs) through sponging miR-9, resulting in the modulation of Cyclin D2 (CCND2) and the regulation of aquaporin 3 (AQP3), which can be regulated by the CREB molecule in the cAMP–PKA pathway." (PMID 37888204, 2023). "In murine models of colon cancer, miR-143 and miR-145 played tumor suppressive functions by targeting Cdk6, CCND2 and E2F3." (PMID 28947999, 2017). "In addition, radiation treatment can promote the radiation resistance of colon cancer stem cells through the activation of JAK2/STAT3/CCND2 signaling pathway." (PMID 36199626, 2022). "Also, MVP-mediated exosomal sorting of miR-193a promotes colon cancer progression through targeting of Caprin1, which upregulates Ccnd2 and c-Myc." (PMID 31402975, 2019). "Meanwhile, the expression of CCND2 has been reported to be increased in chronic B‐cell malignancies and CCND1 elevated in colon cancer, and there is a close relation of CCND1 and CCND2 with clinical results, TNM staging, and metastasis." (PMID 33473276, 2021). "Other findings indicated that EGFR signals could coordinately control multiple G1 regulators via miR-143 and its target K-ras and miR-145 and its targets MYC, cdk6, CCND2 or E2F3, which play a role in cell cycle progression in colon cancer." (PMID 28947999, 2017).
glioblastoma (17 papers, 2010 to 2025). The most malignant astrocytic tumor (WHO grade IV). "CCND2 has a critical role in cell cycle progression, especially in glioblastoma stem cells, and causes G1 arrest in vitro in GSC cells." (PMID 30514244, 2018). "Our finding that the CDK4/MDM2 co-amplicon was associated with CCND2 gain was also seen in glioblastoma multiforme." (PMID 28643781, 2017). "Low levels of GLI1 were found to be associated with high expression levels of Cyclin D2 in the glioblastoma samples (p = 0.007)." (PMID 21059263, 2010). "miR-340 was found to specifically target the 3' UTRs of CDK6, cyclin-D1, and cyclin-D2, leading to the arrest of glioblastoma multiforme (GBM) cells in the G0/G1 cell cycle phase 42." (PMID 33390846, 2021). "More important, high expression of PICOT and low expression of CCND2 correlated with poor patient survival in five different types of human cancers, namely lung and pancreatic adenocarcinoma, glioblastoma, and breast and esophageal cancer." (PMID 31527584, 2019). "It has earlier been reported that cyclin D2 is critical for proliferation of glioblastoma stem cells." (PMID 30555629, 2018). "Additionally, cyclins such as CCND2 are critical in promoting G1/S cell cycle progression and inducing tumorgenesis in mice glioblastoma stem cells." (PMID 39342193, 2024). "Through suppression of several oncogenes including p-AKT, EZH2, XIAP, CDK6, cyclin-D1 and cyclin-D2, overexpression of miR-340 inhibits cancer cell proliferation, migration and invasion, induces apoptosis and autophagy in glioblastoma and miR-340 is a marker for glioblastoma diagnosis and prognosis." (PMID 27036021, 2016). "Moreover, one of the STAT3 targets analysed in this work, Cyclin D2, has recently been reported to be expressed in glioblastoma TICs and to regulate their growth in vivo." (PMID 26486080, 2015). "CDK6 is a validated target in the treatment of Glioblastoma, a kind of brain tumor that is characterized by a high frequency of CDKN2A/CCND2/CDK4/CDK6 pathway dysregulation." (PMID 32858868, 2020). "It has been reported that the miR-610 repressed CCND2 and AKT3 leading to proliferation inhibition on human glioblastoma cells." (PMID 29228616, 2017). "Fourteen high grade astrocytomas (grades III and IV) were assessed for Cyclin D2 and GLI1 expression: only 2 glioblastomas (grade IV) co-expressed Cyclin D2 and GLI1 at high levels." (PMID 21059263, 2010). "PDGFRA amplification has been reported to be more common in diffuse hemispheric gliomas, H3 G34-mutant with glioblastoma-like histology versus tumors with primitive neuronal/neuroectodermal tumor-like features, while CCND2 amplification showed the opposite trend, but this was not seen in our cohort." (PMID 39842935, 2025).
leukemia (14 papers, 2014 to 2023). A malignant (clonal) hematologic disorder, involving hematopoietic stem cells and characterized by the presence of primitive or atypical myeloid or lymphoid cells in the bone marrow and the blood. "Importantly, treatment with DBF causes significant reduction of CCNA1 and CCND2 expression (genes, encoding key regulators of cell cycle transition cyclin A1 and cyclin D2 proteins) in most of the studied leukemia cells." (PMID 34564151, 2021). "This might be the reason why we missed novel recurring but rare mutations in RUNX1/RUNX1T1-rearranged leukemia [CCND2 (6–12%), MGA (8%)]." (PMID 31896782, 2020). "DBF activates the expression of genes encoding the proteins involved in leukemia cell survival, such as KIT, CTNNB1, CCNE1, NFKB1, E2F1, and downregulates the expression of CCND2, CCNA1, and FLT3 genes." (PMID 34564151, 2021). "CCND2, DNMT3B, SOX4, and IKZF2, all previously reported to associate with leukemia development, were found within the positively correlated genes." (PMID 33597968, 2020). "Using in vitro and in vivo screens to identify essential RUNX1/ETO transcriptional targets in AML, Martinez-Soria identify CCND2 as required for leukemia maintenance and self-renewal." (PMID 30300583, 2018). "We also provided intriguing evidence showing that CD274 directly interplays with JNK and enhances its activities to upregulate Cyclin D2 level, leading to the acceleration of leukemia development." (PMID 27855694, 2016). "CDK6 was also found to be positively associated with genes identified to contribute to the development of leukemia, including CCND2, DNMT3B, SOX4, and IKZF2, as well as being negatively associated with anticancer microRNAs, including miR-187, miR-9, miR-582, miR708, and miR-362." (PMID 33597968, 2020). "Moreover, CD274 was directly associated with JNK and enhanced the downstream signaling to increase the Cyclin D2 level, promoting leukemia development." (PMID 27855694, 2016). "The CD274/JNK/Cyclin D2 pathway promotes the cell cycle entry of LICs, which may serve as a novel therapeutic target for the treatment of leukemia." (PMID 27855694, 2016). "The molecular mechanisms by which RUNX1/ETO promotes CCND2 expression highlights the complexity of how leukemogenic transcription factors reprogram the epigenome and establish an aberrant transcriptional network essential for leukemia maintenance and self-renewal." (PMID 30300583, 2018). "Our results highlight that CD274/JNK/Cyclin D2 signaling controls the cell cycle entry of LICs and leukemia development, which may be helpful for the further identification and understanding of the role of other novel surface immune molecules in the maintenance of LIC pool." (PMID 27855694, 2016). "PD-L1 is overexpressed in AML leukemia-initiating cells, where it increases cyclin D2 expression by enhancing JNK phosphorylation, ultimately promoting the entry of leukemia-initiating cells into cell cycle and proliferation." (PMID 37822924, 2023). "The ability of retroviral vector integration to initiate clonal expansion resulting in patient leukaemias with insertions at a subset of integration hotspots (LMO2, BMI1, CCND2) in gene therapy trials indicates the translational relevance of these observations." (PMID 27097319, 2016). "In the ALD trials there were some clones showing clonal dominance with over-representation of the insertion site near SMG6, CCND2, and HMGA2, but this has not led to development of leukemia and may be transient, as was reported for a SIN LV vector used for treating β-thalassemia." (PMID 32322605, 2020).
melanoma (14 papers, 2012 to 2025). A malignant, usually aggressive tumor composed of atypical, neoplastic melanocytes. "Mucosal melanoma cancer cells capable of mediating the compensatory switch from cyclin D1 to cyclin D2, important molecules that cells employ to replicate, exhibited greater resistance to trametinib’s downstream suppressive effects on cyclin D1." (PMID 40723239, 2025). "Despite DNA damage, cell proliferation markers CCND1 and CCND2 were moderately upregulated in treated normal skin cells but downregulated in treated melanoma cells." (PMID 36241419, 2023). "Mucosal melanoma had a significant accumulation of amplification in the regulator of the cell cycle control CCND2." (PMID 32825510, 2020). "The same study demonstrated also that RNF2 supports anchorage independent proliferation of melanoma cells through up-regulation of cyclin D2 due to activation of CCND2 gene." (PMID 29707138, 2018). "Besides RNF6, another RNF protein, RNF2, is also reported to possess dual roles in the regulation of oncogenic gene networks via transcriptional upregulation of Cyclin D2 in melanoma." (PMID 34611311, 2021). "Moreover, we found a statistically significant positive correlation between JAK2 and CCND2 expression in multiple types of cancer, such as melanoma, breast, lung, and renal cancer." (PMID 31511084, 2019). "While also in agreement with findings by other investigators our data show a lack of expression of cyclin-D2 in melanoma B16F10 cells." (PMID 22363217, 2012). "Mucosal melanoma cells lacking sufficient cyclin D2 compensation were more trametinib-sensitive." (PMID 40723239, 2025). "In melanoma, RNF2 has been shown to be oncogenic and prometastatic, and RNF2 can promote metastasis through the inhibition of LTBP2, while its oncogenic function does not require it catalytic activity and RNF2 promotes cell proliferation through direct transcriptional upregulation of CCND2." (PMID 28029659, 2017).
pancreatic cancer (14 papers, 2013 to 2023). "MiR-373-3p inhibits cell propagation and boosts apoptosis in gemcitabine resistance pancreatic carcinoma cells by targeting Ccnd2." (PMID 34440873, 2021). "MiR-373-3p by targeting CCND2 could inhibit cell propagation, migration, and invasion, and boost apoptosis, chemosensitivity, and G0/G1 arrest in gemcitabine resistance pancreatic carcinoma cells." (PMID 33330110, 2020). "Therefore, we determined whether miR-26a could regulate the pancreatic cancer cell cycle through its target genes, cyclin D2 and cyclin E2." (PMID 24116110, 2013). "Of the three criteria, we identified eight genes that were the most highly/frequently methylated in pancreatic cancers (PCDH10, SPSB4, HOXA1, ADAMTS2, BMP3, C13orf18, CCND2, and SEMA5A)." (PMID 32520974, 2020). "Previous studies also showed that the importance of DNA methylation (such as cyclin D2, ppENK, NPTX2) in pancreatic juice for the diagnosis of pancreatic neoplasms." (PMID 24714692, 2014). "For instance, miR-373-3p, downregulated in the gemcitabine resistant pancreatic cancer cell line (GEM-PANC-1), targets CCND2 to conspicuously suppress GEM-PANC-1 cells’ proliferation and invasion, boost their apoptosis, and strengthen their sensitivity to gemcitabine." (PMID 34983307, 2022). "However, our studies showed that cyclin D2 staining was almost negative in pancreatic cancer tissues." (PMID 24116110, 2013). "miR-26a partially influences human pancreatic cancer through the regulation of cyclin E2 and EZH2, but not through cyclin D2." (PMID 24116110, 2013).
thyroid cancer (13 papers, 2013 to 2025). "ROC curve analysis indicated that single or combined analysis of CCND2 and miR-206 had diagnostic value for thyroid cancer, and the diagnostic value of combined detection was higher." (PMID 36694220, 2023). "Compared with the patients with benign thyroid nodules, miR-206 level in FNAC of thyroid cancer patients decreased significantly (P<0.05), while CCND2 level increased significantly (P < 0.05)." (PMID 36694220, 2023). "The AUC of CCND2 level for the diagnosis of thyroid cancer was 0.837 (95% CI: 0.768–0.907), the cut-off value was 1.985, and its sensitivity and specificity was 67.7% and 89.2%, respectively." (PMID 36694220, 2023). "AUC of CCND2 level in the diagnosis of thyroid cancer was 0.837, and the sensitivity and specificity were 67.7% and 89.2%, respectively." (PMID 36694220, 2023). "Third, functional studies are necessary to elucidate the mechanisms by which miR-206 and CCND2 are negatively correlated and regulate the metastasis of thyroid cancer." (PMID 36694220, 2023). "Compared with the patients with benign thyroid nodules, the expression level of miR-206 in fine-needle aspiration cytology of thyroid cancer patients decreased significantly and the expression level of CCND2 increased significantly." (PMID 36694220, 2023). "The AUC of combined detection of miR-206 and CCND2 levels for the diagnosis of thyroid cancer was 0.959 (95% CI: 0.924–0.993), and its sensitivity and specificity was 93.8% and 87.7%, respectively." (PMID 36694220, 2023). "In summary, we found that miR-206 expression was low and CCND2expression was high in FNAC of thyroid cancer patients, and the expression of CCND2 and miR-206 was negatively correlated." (PMID 36694220, 2023). "The AUC of combined detection of CCND2 and miR-206 in the diagnosis of thyroid cancer was 0.959, and the sensitivity and specificity were 93.8% and 87.7%, respectively." (PMID 36694220, 2023). "Consistent with previous reports, in this study, we found that miR-206 level in FNAC of thyroid cancer patients decreased significantly, while CCND2 level increased significantly, compared to the patients with benign thyroid nodules." (PMID 36694220, 2023). "For examples, using papillary (TPC-1) and follicular (FTC-133) thyroid cancer cell lines, HOTAIR was showed to sponge miR-1, activate CCND2 expression, and promote thyroid cancer progression." (PMID 36494673, 2022). "The same responses to manipulation of CCND2 AS1 expression were observed with the BCPAP thyroid cancer cell line." (PMID 32607313, 2020). "miR-1 is able to inhibit thyroid carcinoma cell proliferation and migration by targeting CCND2, CXCR4 and CXCL12." (PMID 24079748, 2013). "miR-206 and CCND2 may become new biomarkers for clinical diagnosis of thyroid cancer based on the fine-needle aspiration cytology of thyroid nodules." (PMID 36694220, 2023). "CCND2 and miR-206 expression was negatively correlated in thyroid cancer tissues." (PMID 36694220, 2023). "Further studies are necessary to determine whether miR-206 and CCND2 can be integrated into the nomogram to improve the accuracy of predicting lymph node metastasis of thyroid cancer." (PMID 36694220, 2023). "CCND2 could be the direct target of miR-206 and miR-206 inhibits cell cycle progression in thyroid carcinoma by downregulating the expression of CCND2." (PMID 36694220, 2023). "CCND2 and miR-206 may be new biomarkers for clinical diagnosis of thyroid cancer." (PMID 36694220, 2023). "Importantly, miR-206 expression was found to be low, whereas CCND2 expression was elevated in the FNAC samples of thyroid cancer patients, indicating a negative correlation between CCND2 and miR-206." (PMID 40346322, 2025). "However, at present, there are no reports on the correlation of miR-206 and CCND2 in FNAC of thyroid cancer." (PMID 36694220, 2023).
thyroid cancer (continued). "Furthermore, CCND2 and miR-206 levels were not significantly correlated with the tumor size of thyroid cancer patients but were correlated with lymph node metastasis, indicating that miR-206 and CCND2 may be involved in tumor metastasis." (PMID 36694220, 2023). "The Pearson correlation analysis showed a negative correlation of CCND2 and miR-206 levels in FNAC of thyroid cancer patients." (PMID 36694220, 2023). "CCND2 and miR-206 levels in FNAC were significantly related to TNM staging and lymph node metastasis (P < 0.05) but not to tumor size in thyroid cancer patients (P > 0.05)." (PMID 36694220, 2023). "By Pearson correlation analysis, we found negative correlation between CCND2 and miR-206 levels in FNAC of thyroid cancer patients (r = − 0.693, P < 0.05)." (PMID 36694220, 2023).